RETN (resistin)
Diseases named in the same sentence as RETN in open-access papers (continued):
Sharing a sentence is not in itself a finding about the gene and the disease.
breast cancer (continued). "This indirect mechanism is noticeably distinct from the direct effect of resistin on breast cancer cells, such as the enhanced tumor growth and metastatic ability of breast cancer cells via toll-like receptor 4 (TLR4) or adenylyl cyclase-associated protein 1 (CAP1)-mediated pathways." (PMID 36104403, 2022). "Thus, high serum resistin concentration has already been correlated with the degree of malignancy, staging, and occurrence of metastases in women with breast cancer." (PMID 36262532, 2022). "Here, we utilized a transwell co-culture model containing patient-derived ADSCs and breast cancer cell lines to investigate their potential interaction, and observed that breast cancer cells co-cultured with resistin-treated ADSCs (R-ADSCs) showed enhanced cancer cell growth and metastatic ability." (PMID 36104403, 2022). "This work underscores the association of autophagy with resistance to anticancer drugs, and suggests that elevated resistin levels in obese breast cancer patients could induce cancer cell chemoresistance through autophagy." (PMID 36291097, 2022). "Subsequent meta-analyses have shown significantly higher resistin levels in breast cancer patients but failed to prove a strong diagnostic and predictive value." (PMID 36077676, 2022). "The rescue of Let-7a inhibited the resistin-mediated tumorigenicity in the breast cancer." (PMID 35804829, 2022). "We investigated whether the mRNA expression of resistin, TNF- α, IL-6, IL-8, and ER-α in PBMCs are associated with breast cancer." (PMID 33517609, 2021). "Recently, resistin has also been proposed as an early breast cancer biomarker." (PMID 34681797, 2021). "Furthermore, similar to leptin, resistin promotes the metastatic potential of breast cancer cells by inducing EMT and stemness." (PMID 34681797, 2021). "They suggested that resistin may be considered as a biomarker for the diagnosis and monitoring of endocrine therapy in patients with breast cancer." (PMID 33517609, 2021). "The association between resistin, TNF-α, IL-6, IL-8, and ER-α expression and breast cancer." (PMID 33517609, 2021). "First, we analyzed clinical correlations between resistin expression and breast cancer." (PMID 32226495, 2020). "Furthermore, increased levels of resistin were reported in breast cancer Caucasian patients, and these levels were correlated with breast tumor growth and aggressiveness." (PMID 33247685, 2020). "Notably, resistin helps to promote tumor growth, drug resistance and metastasis in breast cancer 40,41,42." (PMID 32226495, 2020). "This evidence implicates critical roles for resistin and RETN polymorphisms in breast cancer." (PMID 32226495, 2020). "In an analysis of resistin expression and clinical status in breast cancer tissue samples, high BMI (>24 kg/m2) and resistin positivity was associated with a 5-fold higher likelihood of pathological grade III disease as compared with resistin negativity (OR: 5.020; 95% CI: 1.380-18.259)." (PMID 32226495, 2020). "Taken together, these data demonstrate that adipocytic TAZ/Resistin signaling facilitates breast tumorigenesis, and Resistin neutralization may be a therapeutic strategy for breast cancer treatment." (PMID 33318171, 2020). "We also identified high levels of resistin expression in breast cancer patients." (PMID 32226495, 2020). "Since higher tumor grade and HER2-positive expression are known to be more aggressive and to have a poor prognosis, this finding indicates that the high expression of resistin may be closely related to highly invasive breast cancer and a poor prognosis." (PMID 33313320, 2020). "In addition to patient data, a TNBC-derived cell line MDA-MB-468, derived from an AA breast cancer patient, when treated with resistin, has higher growth and aggressiveness compared to MDA-MB-231 cells derived from a CA patient." (PMID 32824813, 2020).
breast cancer (continued). "In addition, no significant patterns of linkage disequilibrium were observed in any of the RETN genotypes analysed from breast cancer patients." (PMID 32226495, 2020). "In addition, resistin plays a critical role in breast cancer progression, drug resistance, and metastasis." (PMID 30631040, 2019). "Since resistin consequentially increases ezrin phosphorylation, and ezrin knock-down blocks resistin-induced breast cancer cell invasion, PP2A-mediated ezrin phosphorylation may be a critical regulator of breast cancer metastasis." (PMID 31382374, 2019). "In addition, other hormones such as visfatin, plasminogen activator inhibitor-1(PAI-1), and resistin slightly contribute to breast cancer initiation and progression." (PMID 31398937, 2019). "As resistin, like other adipokines is present circulating in the blood, it may act on breast cancer both via its systemic endocrine effects, as well as locally in the tumor microenvironment through paracrine actions." (PMID 30524378, 2018). "We hypothesize that individuals with early breast cancer who have relatively higher resistin levels may provide an environment from which tumours are less likely to metastasize." (PMID 29566726, 2018). "Clinical studies have found that high levels of resistin were associated with the increased risk of breast cancer, and this relationship was independent of age, histological grade, BMI, serum glucose levels, and/or menopause." (PMID 29088874, 2017). "In this study, postmenopausal breast cancer patients were compared to premenopausal breast cancer patients, which may account for the similar resistin levels in most stages." (PMID 27314854, 2016). "Other groups have reported that resistin is a biomarker for postmenopausal breast cancer." (PMID 27314854, 2016). "We also analyzed resistin gene expression by stage to shed light on how resistin expression might change as breast cancer progresses." (PMID 27314854, 2016). "Our results also showed higher resistin expression levels in early stages of breast cancer." (PMID 27314854, 2016). "In this study, we examined resistin expression levels in breast cancer of CA and AA women." (PMID 27314854, 2016). "Because resistin gene expression is higher in early stages (I and II), especially in AA breast cancer patients, it could serve as an early detection biomarker." (PMID 27314854, 2016). "Furthermore, serum resistin levels were higher in postmenopausal breast cancer patients than in healthy controls, indicating that resistin is a serum biomarker for postmenopausal breast cancer." (PMID 27314854, 2016). "The aim of this study was to investigate whether resistin could stimulate invasion and migration of breast cancer cells." (PMID 26729407, 2016). "This suggests that resistin may contribute to racial disparities in breast cancer, or that the elevated levels of resistin may be partially responsible for AA breast cancer phenotype." (PMID 27314854, 2016). "Although an association between resistin and AA breast cancer patients has been shown by our lab, to the best of our knowledge no prior study has linked resistin to AA receptor negative breast cancer subtypes such as ER- and PR-negative cancers." (PMID 27314854, 2016). "Another study also found higher resistin levels in recently diagnosed early breast cancer cases." (PMID 27314854, 2016). "Data revealed that breast cancer subjects had significantly higher systolic blood pressure (p = 0.03), glucose (p = 0.01), triglycerides (p = 0.001), leptin (p = 0.044), resistin (p = 0.04), Ang II (p = 0.02), TNF-α (p = 0.045), and CRP (p = 0.04) than controls." (PMID 23374911, 2013). "A few days in the diagnosis, breast cancer subjects had significantly higher systolic blood pressure (p = 0.03), glucose (p = 0.01), triglycerides (p = 0.001), leptin (p = 0.044), resistin (p = 0.04), ANG II (p = 0.02), TNF-α (p = 0.045), and CRP (p = 0.04) than the controls." (PMID 23374911, 2013).
breast cancer (continued). "Furthermore, resistin has been shown to confer resistance to doxorubicin-induced apoptosis in human breast cancer cells, enhance cisplatin-induced cytotoxicity in lung adenocarcinoma cells, and contribute to 5-fluorouracil chemoresistance in human colorectal cancer cells." (PMID 40002704, 2025). "However, prior MR analysis suggested that both circulating adiponectin and resistin levels are unlikely to causally influence breast cancer risk and, hence, these measures were not included as potential molecular mediators in this analysis." (PMID 37250804, 2023). "Adipokines, including adiponectin and resistin, have previously been linked to breast cancer risk in conventional observational studies and could provide another potential mechanism linking GIPR signaling to breast cancer risk." (PMID 37250804, 2023). "Nevertheless, the biological mechanisms of resistin occurring in the breast tumor microenvironment that contains abundant adipose tissues remain largely unidentified, although elevated resistin expression has been observed in breast tumor and serum samples of breast cancer patients." (PMID 36104403, 2022). "We have previously reported finding much higher levels of resistin expression in breast cancer tissue than in normal breast tissue, but in that study, we did not analyze the relationship between the high expression of resistin and the clinicopathological characteristics of breast cancer patients." (PMID 33313320, 2020). "Thus, the data suggest that therapeutic strategies that effectively inhibit resistin could be useful in breast cancer." (PMID 32226495, 2020). "In addition, resistin facilitates breast cancer progression via TLR4/nuclear factor kappa-light-chain-enhancer of activated B cells (NF-κB)/signal transducer and activator of transcription 3 (STAT3) signaling pathway-mediated induction of mesenchymal phenotypes and stemness properties." (PMID 33313320, 2020). "However, little is known about the participation of resistin in mammary tumors in dogs." (PMID 32903534, 2020). "Because resistin is linked to inflammation and we demonstrated its association with early stage breast cancer, we hypothesize resistin may be linked to early-stage inflammation rather than late-stage metastasis." (PMID 27314854, 2016). "The most prominent increase was observed in the levels of resistin, which has been identified as a biomarker of bladder cancer and is up-regulated in women with polycystic ovarian syndrome but has not been linked directly with mammary cancer." (PMID 20723242, 2010). "Our previous research and other studies have demonstrated that resistin induces EMT, thereby promoting breast cancer metastasis and progression." (PMID 38252319, 2024). "Like resistin, more research is needed to evaluate the role of NEFAs as ligands in the TLR4/NFκB signaling pathway for promoting breast cancer progression." (PMID 37626871, 2023). "In the context of breast cancer, it was discovered that resistin increases the metastatic potential of MCF-7 and MB-231 human breast cancer cells by stimulation of EMT and stemness." (PMID 36077676, 2022). "We also examined the serum levels of resistin and CXCL5 in breast cancer patients by ELISA, and the results showed a positive correlation between the two proteins." (PMID 36104403, 2022). "Our clinical analyses further support this view, with evidence to show a mutual correlation between the expression of resistin, CXCL5, and ERK phosphorylation in the tumor tissues of breast cancer patients." (PMID 36104403, 2022). "Adipokines overexpressed in TNBC include leptin, resistin, NSMPT, LCN2, and apelin, whereas adiponectin and chemerin are significantly downregulated and their protective role against breast cancer has been suggested." (PMID 36077676, 2022). "The purported ortholog receptor of resistin, TLR4, is usually expressed and has recently been identified on multiple tumor cells, including gastric cancer, breast cancer and lung adenocarcinoma." (PMID 36497484, 2022).
breast cancer (continued). "In the same cell lines, resistin promotes EMT and stemness, and hereby breast cancer progression, through activation of toll-like receptor 4 signaling." (PMID 34944905, 2021). "Routine blood analyses, leptin, adiponectin, especially insulin, glucose, resistin, homeostatic model assessment (HOMA), monocyte chemoattractant protein-1 (MCP-1), age, and body mass index (BMI) data can also be used to diagnose breast cancer." (PMID 34730888, 2021). "Here, we uncover its mechanistic significance by characterizing a novel resistin/LIN28A/Let-7a/IL-6/STAT3 signaling axis supporting the growth and stemness of breast cancer cells." (PMID 34572725, 2021). "In this study, our data revealed a significantly positive correlation between positive levels of resistin and ERK1/2 in breast cancer tissues." (PMID 33313320, 2020). "We therefore sought to determine the clinical prognostic significance of our observed highly significant correlation between resistin and EGFR expression in breast cancer tissue." (PMID 33313320, 2020). "Our previous study have shown that EGFR promotes breast cancer invasion through downstream p44/p42 MAPK (ERK1/2) signaling, and resistin is known to enhance angiogenesis in human osteosarcoma cells via the ERK1/2 signaling." (PMID 33313320, 2020). "Our evidence suggests that combined high levels of resistin and EGFR expression correlate with survival in patients with breast cancer." (PMID 33313320, 2020). "It is worthy to note that this study showed a positive correlation between resistin and CEACAM1 in breast cancer patients." (PMID 33247685, 2020). "Breast cancer patients whose tumors were both resistin-positive and strongly EGFR-positive, or were both strongly resistin-positive and strongly EGFR-positive, had worse RFS than all other breast cancer patients." (PMID 33313320, 2020). "Resistin promotes the growth and aggressiveness of breast cancer cells through STAT3 activation, indicating a potential role of resistin, IL-6 and STAT3 in breast cancer racial disparity in AA women." (PMID 32824813, 2020). "Given the recent discovery that resistin binds and acts through the CAP1 receptor, the relative CAP1 gene expression levels were further explored across a panel of 47 breast cancer cell lines." (PMID 30524378, 2018). "We next treated two breast cancer cell lines, MDA-MB-231 (CA origin) and MDA-MB-468 (AA origin) with different doses (0-20 ng/ml) of recombinant human resistin (rh-resistin)." (PMID 25868978, 2015). "The isolated ADSCs were subsequently treated with resistin (R-ADSCs), or without resistin treatment as control, followed by transwell co-culture with human breast cancer cell lines for further investigation of the prolonged effects of resistin." (PMID 36104403, 2022). "The current study suggests that resistin-stimulated ADSCs may interact with breast cancer cells in the tumor microenvironment via CXCL5 secretion, leading to breast cancer cell malignancy." (PMID 36104403, 2022). "These newly discovered pathways of resistin may be mediated through ADSCs in the breast tumor microenvironment via CXCL5 secretion, leading to the malignant behaviors of breast cancer cells." (PMID 36104403, 2022). "The cancer promoting effect via the proposed route of resistin-ADSC-CXCL5 may involve activation of the ERK pathway and epithelial-to-mesenchymal transition in breast cancer cells." (PMID 36104403, 2022). "In addition, clinical analysis revealed a positive correlation between the expression of resistin and CXCL5 in both tumor tissues and serum specimens of breast cancer patients." (PMID 36104403, 2022). "Based on the results of our preclinical investigation, we further analyzed whether clinical correlations occur between the expression levels of resistin, CXCL5, and ERK phosphorylation in breast cancer patients by immunohistochemistry." (PMID 36104403, 2022).
breast cancer (continued). "Furthermore, resistin was proved to accelerate EMT and breast cancer cell stemness by toll-like receptor 4 (TLR4)-induced NF-κB activation." (PMID 35701840, 2022). "We have demonstrated that the mRNA expression of resistin and ILl-6 in PBMCs of women with breast cancer was significantly high in comparison to women without breast cancer." (PMID 33517609, 2021). "Additional and larger epidemiological studies are warranted to investigate the potential role of adiponectin and resistin as prognostic markers, primarily in ERPR negative breast cancer, where risk of mortality is high." (PMID 34876619, 2021). "The expression of resistin was found significantly higher in estrogen negative breast cancer patients and was reported as a potential biomarker for early cancer detection." (PMID 34588926, 2021). "Furthermore, resistin is found to promote EMT and CSC-like properties in breast cancer cells through a TLR4/NF-κB/STAT3 signaling pathway." (PMID 33123472, 2020). "Spearman correlation analysis revealed significantly positive correlations between strongly positive levels of resistin expression and EGFR-positive or strongly positive expression in breast cancer tissue specimens (r = 0.318 and P < 0.001 and r = 0.207 and P < 0.001, respectively)." (PMID 33313320, 2020). "Rates of positive and strongly positive resistin expression were significantly higher in breast cancer tissue than in the adjacent nontumor tissue (83.2% vs. 23.8% and 20.9% vs. 0.0%, respectively; P < 0.001 for both comparisons)." (PMID 33313320, 2020). "Spearman correlation analysis revealed significantly positive correlations between positive levels of resistin expression and EGFR-positive or strongly positive expression in breast cancer tissue specimens (r = 0.250 and P < 0.001 and r = 0.166 and P = 0.001, respectively)." (PMID 33313320, 2020). "Similarly, a positive correlation was observed between staining intensity scores of resistin and EGFR in breast cancer tissues (r2 = 0.1124, P < 0.001)." (PMID 33313320, 2020). "Interestingly, very recently a report has emerged which establishes a role of resistin in inducing EMT and stemness of breast cancer cell, which it accomplishes by being a ligand for toll-like receptor-4 (TLR4), and by stimulating NF-κB-STAT3 signaling." (PMID 30131543, 2018). "Several studies have reported upregulated systemic resistin levels in breast cancer patients, while others have not shown the same correlation." (PMID 30524378, 2018). "Yet, the impact by resistin and in particular CAP1 on breast cancer remains elusive." (PMID 30524378, 2018). "Also, breast cancer patients had lower concentrations of adiponectin and higher concentrations of leptin, IL-6, IL-8, TNF-α, resistin and visfatin than controls." (PMID 29088874, 2017). "Importantly, resistin-induced autophagy in MCF-7 and MDA-MB-231 cells inhibited apoptosis mediated by doxorubicin, a drug used in adjuvant chemotherapy and recommended as a first-line treatment for breast cancer." (PMID 36291097, 2022). "In addition to interferon, the TME of AA women with breast cancer has a higher abundance of the pro-inflammatory markers IL6 and resistin compared to EA women which could contribute to racial disparities in clinical outcomes." (PMID 34071280, 2021). "Our previous study found upregulated resistin expression in breast cancer tissue than in normal breast tissue, but in that study, we did not analyze the relationship between the high expression of resistin and the clinicopathological characteristics of breast cancer patients." (PMID 33313320, 2020). "Separate analyzes using the independent TCGA 1,105-sample breast cancer data set showed a positive correlation between the CAP1 mRNA expression and protein levels (Pearson's r = 0.36), while only a weak positive correlation between CAP1 and resistin (RETN) tumor expression (Pearson's r = 0.16)." (PMID 30524378, 2018).